CD86 (CD86 molecule)
Diseases named in the same sentence as CD86 in open-access papers (continued):
Sharing a sentence is not in itself a finding about the gene and the disease.
infection (continued). "The results demonstrated that the levels of pStat3and pNF-κB p65 were significantly upregulated after ME49 infection, and downregulated after depletion of BFD2 Simultaneously, qRT-PCR was used to quantify Il1b, Ifng, and Cd86 transcripts in cells infected with T. gondii." (PMID 40906736, 2025). "This abortive infection induces the activation of monocytes, which subsequently produce various proinflammatory cytokines and chemokines and express MHC class II and the costimulatory molecules CD80 and CD86, which are important for T-cell activation." (PMID 41280933, 2025). "The expression level of CD86, a marker of M1 macrophages, remained consistently higher in AIM KO BMDMs than in wild-type BMDMs, including in the uninfected state and up to 2 days after infection, with the difference increasing over time." (PMID 40391046, 2025). "CD163+ and CD86+ TAMs were significantly more abundant in H.pylori-positive patients compared with those without infection (P < 0.001)." (PMID 41395618, 2025). "We showed that the infection of moDC with L. mexicana downregulated the expression of CD86 but not of MHCII." (PMID 38787051, 2024). "Co-stimulatory molecules such as CD86 were increased in PVM-infected mice compared to mock infection, but this was not modified further by inhaled GM-CSF administration." (PMID 39439800, 2024). "In addition, CD86, the target gene of TCONS_00007391, was also significantly up-regulated in an APEC dose-dependent and infection time-dependent manner." (PMID 38326918, 2024). "While the percentage of CD11b+ cells were not different between genotypes, we found that CD11b+Tln1-deficient BMmacs expressed higher levels of CD86, but not MHCII, compared to Tln1fl/fl BMmacs with infection." (PMID 38102166, 2023). "In addition, the transcriptional levels of the M1 marker, iNOS, and the M2 marker, Arginase-1, in the macrophages collected from the infected livers, as measured by RT-qPCR, showed the same trends as the CD86+ and CD206+ expression during the infection course." (PMID 36668953, 2023). "Thus, we evaluated the expression of two M1 genes (TNFα and CD86) and two M2 genes (IL-10 and CD206) at different time points post-infection under normoxic and hypoxic conditions in human and bovine macrophages." (PMID 36793725, 2023). "Although the infection rates of SARS-CoV-2 in iMΦ were approximately 11% and 4% for Delta and Omicron, respectively, the infection did activate iMΦ to upregulate mRNA expression of the M1 phenotype marker CD86." (PMID 36883057, 2023). "Cells containing either gRNA-Cd274 or gRNA-Cd86 were uniformly distributed across the four cell states, suggesting that expression of PD-L1 or CD86 per se, and infection with lentivirus do not affect the cell state." (PMID 37813864, 2023). "However, infection of BMDCs with LDPm led to a gradual decrease in LPS-stimulated CD40, CD80, and CD86 expression, with peak inhibition observed at 24 h postinfection." (PMID 35924848, 2022). "The expression of activation markers CD80, CD86 and HLA-DR was strongly increased on macrophages following infection compared to the non-infected control." (PMID 35615366, 2022). "Notably, we found that the expression of specific markers of M1 type microglia (Aif1, Cd86, Cd40, Ccl2, Ccr2, Cx3cr1, IL-1β, IL-6, and NOS2) was elevated post infection." (PMID 36618398, 2022). "Nevertheless, the cDC2 subset was recruited at higher numbers to ICAM-1/2-/- LNs following PR8 infection, and were hyperactivated, as evident by their significantly elevated levels of the major co-stimulatory molecules CD80 and CD86, as well as elevated IL-6 production." (PMID 36895258, 2022). "Transcripts indicating antigen presentation (Cd11c, Cd80, and Cd86) are enriched in non-infected cells at later stages of infection." (PMID 35663950, 2022). "Importantly, B7-H4−/− infection further regulated the expression of molecules (CD80, CD86, and MHC-II or HLA-DR), enzyme IDO, and cytokines (IL-10 and IL-12) in dDCs." (PMID 35505420, 2022).
infection (continued). "In addition, elevated expression levels of CD86 and MHCII were noted in response to these infections (online suppl." (PMID 35249041, 2022). "Of note, the CD86+ cDCs were sustained at high levels regardless of the infection status, indicating that the T-cell priming function of cDCs was not solely dependent upon the scrub typhus infection." (PMID 34276693, 2021). "Interestingly, exosomes secreted by microglia during TMEV infection had increased levels of co-stimulatory molecules, CD80, CD86, CD40, on the surface compared to exosomes secreted by microglia during mock infection." (PMID 34485270, 2021). "Treated and untreated infected mice were sacrificed 96 hours and 2 weeks after infection, their lungs removed, macerated and CD11c+ lung myeloid cells analyzed by flow cytometry for the expression of activation markers (IAb, CD40, CD80, and CD86)." (PMID 33936043, 2021). "Surprisingly, treatment initiated in hyperacute phase of infection did not prevent downmodulation of CD86 on APCs, rather expression resembled that of treatment-naïve infection for monocytes and mDCs." (PMID 34630420, 2021). "Furthermore, our results demonstrate that despite an upregulation of CD40, CD169+ M2 macrophages downregulate CD86 and MHC-II expression upon infection with SARS-CoV-2." (PMID 34122407, 2021). "This may be because EBV activates B lymphocytes upon infection, leading to increases in the abundances of their activator antigens CD5, CD80, and CD86, which play major roles in maintaining immune stability." (PMID 32149157, 2020). "According to recent studies, crosstalk occurs between NK cells and macrophages, which plays an important role in anti-infection responses, and macrophages are activated by IFN-γ, which is mainly produced by NK cells and CD4+ T cells via increasing receptors such as CD80, CD86 and MHC II." (PMID 33327533, 2020). "Induced expression of CD80 and CD86 was shown to enhance infection of species B Ads, but not HAdV-C5." (PMID 32957644, 2020). "As we expected, the expression and MFI of plasma cell-expressing CD40 and CD86 in BTNF-/- and TNF-/- mice were comparable to those of TNFf/f mice at week 3 after infection." (PMID 32742607, 2020). "Infection readily induces the upregulation of CD40 and B7.2 (CD86) at even higher levels than cDCs." (PMID 32545470, 2020). "But while infection with Msm WT and Msm ΔespG3::espG3 strongly increased expression levels of the T cell co-stimulatory molecule CD86, the Msm ΔespG3 strain failed to do so." (PMID 32582196, 2020). "After infection with H-1PV, the level of CD80 and CD86 rose 8-fold and CD83 2-fold." (PMID 31192129, 2019). "Indeed, upon infection, eosinophils upregulate expression of the Major Histocompatibility Complex (MHC) class I and CD86 antigen presentation markers, leading to activation and enhancement of the CD8+ T cell response." (PMID 30787331, 2019). "SFTSV infection of activated macrophages resulted in the down-regulation of surface HLA-DR and CD86 but not CD40." (PMID 31156641, 2019). "Additionally, RHΔrop16 strain infection significantly promoted M1 macrophage phenotypes of CD80 and CD86, and decreased CD206 expression of M2 macrophages, with upregulation of the iNOS and downregulation of the Arg-1 expression in placental homogenates." (PMID 32082272, 2019). "Infection with the S. aureus USA300 WT or the S. aureus Δαβδ mutant strain induced the up-regulation of MHCII, CD86, CCR7, CD80, CD40, and PD-L2 on all DC subsets in the spleen starting 6 h pi compared to PBS-treated mice as analyzed by flow cytometry staining." (PMID 31134074, 2019). "Although CD86 possibly takes center stage in this context, the equivalent expression of other costimulatory molecules can lead to the early production of IFN-γ or IL-4 during infection by L. major depending on the experimental model." (PMID 30873156, 2019).
infection (continued). "Deficiency or knockdown of GDF15 in DCs increased the expression of MHCII, CD40,CD80 CD83, and CD86, while over expression of GDF15 either by using GDF15 TG DCs or infection with GDF15-Ad reduced the expression of these molecules, in comparison with WT untreated DCs." (PMID 30425709, 2018). "In addition, K5, which is expressed very early upon infection and at a low level during latency, can down-regulate expression of ICAM-1 (CD54) and B7-2 (CD86), which are ligands for natural killer (NK) cell mediated cytotoxicity." (PMID 28881567, 2017). "Infection of neonates did not stimulate expression of the co-stimulatory molecule CD86 by dendritic cells and neonates exhibited a diminished T cell response compared to adult mice." (PMID 28060871, 2017). "To phenotypically characterise pDC during early P. falciparum infection we assessed maturation markers; CD86, CD40, CD80, HLA-A,B,C, HLA-DR and CD123 (IL-3Rα) expression on pDC before and at peak-infection for participants infected with either 150 pRBC or 1,800 pRBC." (PMID 28572564, 2017). "CD11c and CD86 were increased on RFP+ cells in both NaLm and LmLm mice, however, CD86 was higher on RFP+ cells from LmLm mice, suggesting that infected monocytes at secondary sites of infection undergo enhanced maturation versus those at primary sites." (PMID 28666021, 2017). "We showed that cultured primary human macrophages, upon infection with some representative pathogenic arenaviruses, failed to elevate the levels of activating markers CD80, CD86 and of cytokines (e.g., IFNβ, TNFα, IL-1β, IL-6, and IL-8)." (PMID 28498311, 2017). "Similarly, ΔN146 infection resulted in significant increase in the number of CD40-positive and CD86-positive CD11c+ DCs compared to the mock group." (PMID 28150813, 2017). "MHC class II, CD86 and CD40 expression on splenic pDCs remained unchanged during S. mansoni infection, indicating that the liver is a major site of pDC activation in this infection model." (PMID 26657145, 2016). "Although hepatic cDCs did not upregulate MHC class II or CD86 in response to infection, surface levels of these markers were significantly increased on hepatic pDCs isolated from S. mansoni-infected mice compared with naive mice." (PMID 26657145, 2016). "RRV infection of either mouse strain did not alter pDC expression of CD86 on day 5 or day 7 post infection." (PMID 27405244, 2016). "Briefly, at 48 hours post infection (hpi), 78.7% of WNVNY99-infected MoDCs and 84.5% of WNVNSW2011-infected MoDCs showed CD80 upregulation, and 93.9% of WNVNY99-infected MoDCs, 95.8% of WNVNSW2011-infected MoDCs showed CD86 upregulation." (PMID 25884341, 2015). "AAL and AAS treatment induced maximum up-regulation of CD80 (11.7% and 15.7%) and CD86 (12.6% and 15.4%) expression along with CD80/86 (13.1% and 17.0%) co-expression in comparison with infection control where as in AMB and ART treated groups, the effect was less pronounced." (PMID 25568967, 2015). "Mice that were genetically engineered to lack two co-stimulatory molecules called CD80 and CD86 failed to accumulate active CD8+ T cells in response to infection with a herpes-like virus." (PMID 26263500, 2015). "Surprisingly, while infection with Y strain and Col cl1.7 both led to an increase in the intensity of expression of HLA-DR and TLR-2, the two isolates affected differently the expression of CD80 and CD86." (PMID 26147698, 2015). "Infection of VSV was able to upregulate small but significant amount of CD86 on AC-6-pDCs although there was no detectable change on MHC class II expression." (PMID 26263178, 2015). "Since CD86 blockade led to increased morbidity without any change in viral clearance, we wanted to determine if CD86 blockade during the resolution phase of infection delayed recovery by affecting the extent or characteristics of pulmonary inflammation." (PMID 25144228, 2014).
infection (continued). "CD86, however, was not reduced from the macrophage surface after infection with either MCMV-GFPΔm144-m148 or MCMV-GFPΔm149-m153, mutants that do lack the m147.5 gene." (PMID 24626474, 2014). "We could detect an initial (day 1 p.i.)fall in CD86 expression in the MHCII+high co-infected animals, lower than both single infections (Wilcoxon rank sum test, P = 0.03 and 0.005, B. duttonii and P. berghei respectively)." (PMID 25075973, 2014). "Surface expressions of MHCII, CD80 and CD86 were increased after infection, indicating maturation of cells, but were not appreciably different between the genotypes." (PMID 24728387, 2014). "Due to high levels of capillary leak and alveolar injury at the time of administration (day 10 post infection), lung specific blockade of CD86 would not be practicable since intranasal administration of αCD86 would readily enter the systemic circulation." (PMID 25144228, 2014). "There were differences in the expression MHC II, CD40 and CD86 between the naïve APC populations, and changes in expression of these markers suggested that at least a portion of each of the cell populations responded to the infection." (PMID 23390557, 2013). "Although CD80 and CD86 were expressed on each of the cell populations, there was little increase in the expression of CD80 or CD86 in any of the cell populations in response to infection." (PMID 23390557, 2013). "Do9432, which showed the highest susceptibility to HIV replication, expressed high levels of CD86 and CD69 in the absence of infection." (PMID 24341794, 2013). "Upon pathogen infection, DCs capture foreign antigen and undergo maturational changes including increased surface expression of major histocompatibility complex (MHC) and costimulatory molecules, such as CD40, CD80, and CD86." (PMID 23301113, 2013). "To investigate whether maturation is induced in BDCA1+ mDCs upon infection we determined expression levels of co-stimulatory (CD80 and CD86) and co-inhibitory (PDL1) molecules on their cell surface." (PMID 23638101, 2013). "Thus, infection of MDDC with Candida albicans augments HIV trans infection of T cells in relation to increases in expression of CD80 and CD86 on the DC." (PMID 24278768, 2013). "MVA-C infection of human monocyte derived dendritic cells (moDCs) induced the expression of HIV-1 antigens at high levels from 2 to 8 hpi and triggered moDCs maturation as revealed by enhanced expression of HLA-DR, CD86, CD40, HLA-A2, and CD80 molecules." (PMID 22536391, 2012). "Neither CD86 nor HLA-DR expression on pDCs were dependent on age group, infection status or the interaction of these variables." (PMID 23029585, 2012). "The inducible expression of positive and negative costimulatory molecules (CD80, CD86, B7-H1) by microglia was also examined following infection to gain further insight into their function during acute TMEV infection in vivo." (PMID 21494618, 2011). "When comparing children undergoing infection from each ethnic group, the Fulani exhibited higher levels of HLA-DR and CD86 on the BDCA-1+, BDCA-2+ and BDCA-3+ DCs but not on CD16+ DCs as compared to the infected Dogon children." (PMID 21483827, 2011). "Flow cytometry analysis of cell surface expression markers CD40, CD54, CD80, CD83, CD86 and HLA DR in infected DC revealed significant (p < 0.05) up regulation following infection with M. tuberculosis in comparison to immature DC with no stimulation." (PMID 21777464, 2011). "When comparing children undergoing infection from each ethnic group, the Fulani exhibited higher levels of HLA-DR and CD86 on classical but not on inflammatory monocytes as compared to Dogon children." (PMID 21483827, 2011). "The absence of CD28, CD40, CD40L, CD80/CD86 or 4-1BBL did either not affect viral replication in the early phase of infection or early viral titers were rather increased." (PMID 19621080, 2009).
infection (continued). "CD40 and CD86 were increasingly expressed during the course of infection (data not shown); in contrast, CD80 failed to be upregulated." (PMID 19436710, 2009). "For late P. yoelii infection, the expression of CD40 and CD86 on CD11c+ splenocytes was not significantly upregulated in response to parasite infection (average parasitaemia, 21.62)." (PMID 19077314, 2008). "Our observation of increased intermediate monocytes (with presumably higher MHC-II, CD80, and CD86 expression) in the FABP-immunized group suggests ongoing antigen immune activation, consistent with prior reports that intermediate monocytes upregulate these markers during infection or immunization." (PMID 41376640, 2025). "Specifically, post-infection, the number of dendritic cells (DCs)—key initiators of immune responses—was significantly reduced, although the expression level of the surface activation marker CD86 showed no significant change." (PMID 41441659, 2025). "Finally, CD206 and CD86 did not present differences in their expression among monocytes ́ subpopulations (C=I=NC) neither in the entire cohort nor in infection stages (p > 0.05; ANOVA)." (PMID 39766068, 2024). "Moreover, the infection of moDC downregulates some features of DC maturation such as IL-12 p40 transcription and secretion and CD86 expression but not MHCII presence." (PMID 38787051, 2024). "Therefore, the lower levels of CD86 and CD80 observed may be due to an abrogation of their induction following ZH501 infection." (PMID 38392897, 2024). "Interestingly, pDC showed increased MFI for CD40, CD80, CD86, and MHC-II on the molecules positive pDC, respectively, after BCG immunization, especially at 4 h and 12 h post-infection, suggesting high expression levels of these molecules on the limited positive pDC." (PMID 36977141, 2023). "No obvious change in CD40 or CD86 was detected in LN MΦs during infection." (PMID 38012553, 2023). "Interestingly, determination of the level of expression of macrophage antigen presentation/processing and activation markers (MHCII, CD80, CD86 and CD40) by flow cytometry after 48 h of infection revealed that all markers were significantly increased in cells infected with the sucT mutant." (PMID 37669276, 2023). "However, no expression of CD86 was induced at 48 hours of infection, but CD206 expression was significantly upregulated." (PMID 37325614, 2023). "In addition, the functional state CS3 is the most different with the expression of Cd86, Cd4, and especially Ccl22, suggesting this state to be actively recruiting other cells, such as invariant NKT or regulatory T cells, in response to the infection." (PMID 34404761, 2021). "Moreover, the recovery of circulating pDC numbers was accompanied by a decreased expression of CD86 and CD274, suggesting that the antigen presentation or tolerogenic function of pDCs might be limited during the acute phase of the infection." (PMID 34276693, 2021). "Interestingly, pDC CD86 expression was not altered in viraemic infection and lower expression levels were only observed following very early ART." (PMID 34630420, 2021). "The expression of a co-stimulatory marker, indicated by CD86, was increased on pDCs during scrub typhus infection, which reflected their T-cell co-stimulatory function, consistent with previous studies on human immunodeficiency virus (HIV) and hepatitis C virus (HCV) infections." (PMID 34276693, 2021). "At 6–9 months, multivariant infection was characterized by increased frequency of plasmablasts (p = 0.05) which in chronic HIV infection mainly produce autoreactive and polyreactive antibodies, and an increase in activated B cells that express the activation marker CD86 (p<0.001)." (PMID 32886726, 2020). "Interestingly, circulating and hepatic Ly6Chi monocytes from gonadectomized male mice, which received the testosterone treatment showed higher expression of the costimulatory receptor CD86, independent of infection and/or organ." (PMID 32651360, 2020).